IRF7 (interferon regulatory factor 7)
Diseases named in the same sentence as IRF7 in open-access papers (continued):
Sharing a sentence is not in itself a finding about the gene and the disease.
HIV-1 infection (15 papers, 2009 to 2025). The type species of lentivirus and the etiologic agent of acquired immunodeficiency syndrome (AIDS). "The rare allele A of two IRF-7 SNPs, rs12272434 and rs12290989, both located at exon/intron boundaries, were significantly associated with impaired levels of IFNα production by human plasmacytoid dendritic cells (pDCs) in response to human immunodeficiency virus 1 (HIV-1) infection." (PMID 31574965, 2019). "We next evaluated the effect of IRF7 expression on IFN-α/β transcription induced by HIV-1 infection." (PMID 37328105, 2023). "Further functional studies are required to determine how IRF7 promotes HIV-1 infection in monocytic cells." (PMID 37328105, 2023). "One of explanations for this phenomenon is that the effects of opiate use and HIV-1 infection on IRF7 expression are multifaceted." (PMID 29026137, 2017). "Knocking down IRF-1 with siRNA decreased the HIV-1 infection levels, whereas the IRF-7 knockdown increased HIV-1 infection levels." (PMID 19404407, 2009). "Despite our extensive studies, we cannot exclude the potential roles of TLRs in the regulation of IRF-1 and IRF-7 during HIV-1 infection." (PMID 19404407, 2009). "The expression levels of IRF-1 and IRF-7 increased upon HIV-1 infection and the increase occurred as early as 3 days after infection." (PMID 19404407, 2009). "Moreover, HIV-1 infection has been shown to stimulate the IRF7-mediated IFN-I response, and IRF7 knockdown reduced HIV-1 infection in human primary macrophages." (PMID 37328105, 2023). "Furthermore, we showed that IRF7 is required for efficient HIV-1 infection and viral transcription in THP-1 cells." (PMID 37328105, 2023). "Furthermore, we investigated the role of SAMHD1 inhibition of IRF7-mediated IFN-I induction during HIV-1 infection." (PMID 37328105, 2023). "Moreover, certain ‘common ISGs’ that were upregulated by HIV-1 infection (IRF7, TRIM25, MYD88, MX2, LGALS9, and SP100) exhibited a strong anti-HIV-1 effect in THP-1 cells." (PMID 30915053, 2019). "Interestingly, the authors revealed that 3-MA treatment during HIV-1 infection reduces IFN regulatory transcription factor 7 (IRF7) phosphorylation, which is necessary for the translocation of IRF7 to the nucleus and subsequent stimulation of IFNα expression." (PMID 28946621, 2017). "The results showed that either opiate use (Opiate+ HIV−) or HIV-1 infection (Opiate− HIV+) could lead to significantly decreased expression of IRF7 protein compared to the control group (P < 0.05)." (PMID 29026137, 2017). "In addition, opiate use plus HIV-1 infection (Opiate+ HIV+) resulted in lower expression of IRF7 protein compared to the Opiate+ HIV− or Opiate− HIV+ group (P < 0.05)." (PMID 29026137, 2017). "Our investigation showed that opiate use and HIV-1 infection up-regulated IRF7 expression at mRNA level; however, both of them could down-regulate IRF7 expression at the protein level." (PMID 29026137, 2017). "However, it remains unclear how m6A modifications of HIV-1 RNA reduce phosphorylation of IRF3 and IRF7 during early stage of HIV-1 infection." (PMID 33690734, 2021). "Therefore, these polymorphisms may affect the ability of human subjects to control HIV-1 infections, reinforcing the role of IRF-7 in controlling viral infections." (PMID 31574965, 2019). "On the one hand, opiate use and HIV-1 infection could induce the expression of IRF7 mRNA." (PMID 29026137, 2017). "To better understand the role of IRF7 on SAMHD1-mediated suppression of IFN-I signaling during HIV-1 infection, we first examined the effect of IRF7 KO on HIV-1 infection." (PMID 37328105, 2023). "Compared to our findings, IRF7, TRIM25, and MX2 were the ‘common ISGs’ that exhibited anti-HIV-1 effects in MT-4 cells and were upregulated by HIV-1 infection." (PMID 30915053, 2019).
HIV-1 infection (continued). "They found that persistent HIV-1 infection in humanized-mice led to induction of IFNs and ISGs including MX2, IFITM3, Trim22, ISG15, OAS1, and IFN regulatory factor 7 (IRF7) both in peripheral blood mononuclear cells (PBMCs) and in the spleen." (PMID 30665429, 2019). "We have demonstrated that HIV-1 infection increased STAT1 phosphorylation at Tyr701 and total STAT1 expression and that the activation of STAT1 is essential for IRF-1 and IRF-7 expression and TRAIL induction." (PMID 19404407, 2009). "Nevertheless, our data strongly support a critical role for IRF-1, IRF-7, and type I IFNs in the induction of macrophage STAT1 activation during HIV-1 infection." (PMID 19404407, 2009). "The upregulation of IRF-1, IRF-7, and TRAIL, and the activation of STAT1 by HIV-1 infection was reduced by the treatment of type I interferon neutralizing antibodies." (PMID 19404407, 2009). "The role of IRF-1, IRF-7, type I IFNs, and STAT1 in the regulation of TRAIL during HIV-1 infection of macrophages is important and adds to our understanding of pathogenesis of HIV-1." (PMID 19404407, 2009). "The upregulation of RIG-I by HIV-1 infection in macrophages is novel and interesting, however its relationship with IRF-1 and IRF-7 regulation remains the subject of further investigation." (PMID 19404407, 2009). "We found that HIV-1 infection also induced interferon regulatory factor (IRF)-1, IRF-7 gene expression and signal transducers and activators of transcription 1 (STAT1) activation." (PMID 19404407, 2009). "We found that THP-1 cells lacking IRF7 expression had reduced HIV-1 infection and viral transcription compared to control cells, indicating a positive role of IRF7 in HIV-1 infection." (PMID 37328105, 2023). "A direct correlation between IRF7 expression and HIV-1 latency reactivation in myeloid latently infected cells has also been reported, further supporting the positive role of IRF7 on HIV-1 infection and gene expression." (PMID 37328105, 2023). "We further examined whether opiate use and/or HIV-1 infection affects the expression of IFN-α, an important type I interferon that is regulated by IRF7." (PMID 29026137, 2017). "HIV-1 infection induced IRF-1 and IRF-7 gene expression and STAT1 phosphorylation in macrophages." (PMID 19404407, 2009). "HIV-1 infection induced IRF-1, IRF-7 gene expression and activated STAT1 in macrophages." (PMID 19404407, 2009). "Furthermore, the upregulation of IRF-1, IRF-7, TRAIL, and the activation of STAT1 by HIV-1 infection was reduced by the treatment of type I interferon (IFN)-neutralizing antibodies." (PMID 19404407, 2009). "Consistent with TRAF3 upregulation, we found an increase in phosphorylated IRF3 and IRF7 at 7-days post HIV-1 infection, as compared to uninfected control cultures and with 3 dpi-infected cultures, although no significant changes were observed at the transcriptional levels for both IRF3 and IRF7." (PMID 41041557, 2025). "In contrast to IP-10, expression of IFN-β was robustly attenuated by knockdown of IRF3, IRF5, or IRF7 expression in HIV-1–infected MDMs, suggesting a selective and nonredundant role of IRF5 in mediating a proinflammatory response to HIV-1 infection in macrophages." (PMID 40493408, 2025). "These upregulated genes were primarily ISGs, including IRF5 and IRF7, as well as several known IRF5 target genes, including CCL5, CXCL16, and IL23A, suggesting that MDMs from older individuals display an enhanced IRF5-dependent innate immune response to HIV-1 infection." (PMID 40493408, 2025). "We showed that HIV-1 infection was significantly impaired in cells lacking IRF7 expression." (PMID 37328105, 2023). "HIV-1 infection was previously reported to stimulate type I IFN production through the IRF pathway, which we show is potentiated by Vpx, thus it remains possible that NF-κB responses are impaired in the presence of infection with Vpx, whereas the IRF3/IRF7 signaling remains active." (PMID 33563288, 2021).
HIV-1 infection (continued). "Our monocyte methylation data in AHI further highlight the function of the IRF7 gene in HIV-1 infection, provide additional evidence that the IRF7 plays a key role during the earliest stages of HIV-1 infection, and suggest that DNA methylation plays a key role in regulation IRF7 gene activity." (PMID 34388205, 2021). "When we applied siRNA to knockdown IRF-1, IRF-3, or IRF-7 gene expression in human macrophages, the increase of TRAIL expression by HIV-1 infection was reduced by the IRF-1 and the IRF-7 knockdown, but not by the IRF-3 knockdown." (PMID 19404407, 2009). "HIV-1 Tat induces transcription from the IRF7 promoter and induces the expression of IFN stimulated genes in the absence of HIV-1 infection, suggesting that HIV-1 may co-opt the function of antiviral host genes for proviral functions." (PMID 37328105, 2023). "Of note, both THP-1 Ctrl and SAMHD1 KO cells lacking IRF7 expression showed lower levels of HIV-1 infection, suggesting that IRF7 may promote HIV-1 infection in THP-1 cells." (PMID 37328105, 2023).
glioma (14 papers, 2016 to 2025). A benign or malignant brain and spinal cord tumor that arises from glial cells (astrocytes, oligodendrocytes, ependymal cells). "Key hub genes such as TLN1, FN1, and IRF7 were associated with glioma progression and poor prognosis." (PMID 40365337, 2025). "In summary, our study identifying the GRN in patients with wild‐type IDH gliomas provided exciting results and showed that the IRF7‐associated IFN signaling pathway may influence patient prognosis." (PMID 39492838, 2024). "Therefore, further research is needed to validate these findings and gain a deeper understanding of the mechanisms underlying IRF7 regulation in IDH wild‐type gliomas." (PMID 39492838, 2024). "Moreover, high IRF7 expression may be associated with wild‐type gliomas, which typically have a worse prognosis." (PMID 39492838, 2024). "Subsequently, we used various machine learning algorithms to screen and construct a glioma prognostic model centered on IRF7 target genes." (PMID 39492838, 2024). "We established a subcutaneous xenograft model to assess the role of IRF7 in glioma progression in vivo." (PMID 39492838, 2024). "Post‐excision, IRF7 xenografts weighed less and were smaller than their control counterparts, indicating that IRF7 potentially promoted tumor effects by impeding glioma growth." (PMID 39492838, 2024). "Inflammatory signaling mediated by IRF7 promotes neural glioma stem cells and angiogenesis and serves as a major driving force in the progression and cellular heterogeneity of brain tumors." (PMID 39492838, 2024). "Third, although some IRF7 cellular mechanistic studies have been conducted, further mechanistic validation in microglial cell lines and with a glioma TME is needed." (PMID 39492838, 2024). "By integrating bulk RNA‐seq with scRNA‐seq data, we have further delineated the role of IRF7 in IDH wild‐type gliomas." (PMID 39492838, 2024). "Compared to the IDH‐mutant cell subsets, IRF7 was highly expressed in IDH wild‐type microglial gliomas." (PMID 39492838, 2024). "Previous studies have demonstrated that IRF7 is a critical determinant of glioma progression and heterogeneity of glioblastoma." (PMID 39492838, 2024). "In vitro culture of glioma cells transfected with overexpressed/silenced IRF7 plasmids and in vivo study of nude mice injected with tumor cells." (PMID 37251373, 2023). "IRF7 was shown to promote glioma cell invasion as well as chemoresistance and radiation resistance by inhibiting the expression of argonaute 2 (AGO2), a regulator of microRNA maturation, biosynthesis, and function." (PMID 37251373, 2023). "Meanwhile, we observed that D2HG cannot further promote the replication in IRF3-knockdown or IRF7-knockdown glioma cells." (PMID 37880243, 2023). "Interferon regulatory factor 7 (IRF7) can enhance glioma cell invasion, chemoresistance, and radioresistance." (PMID 27344170, 2016). "The CCK‐8 assay was performed to assess the role of IRF7 in glioma cell proliferation." (PMID 39492838, 2024). "Additionally, IRF7 was shown to promote the proliferation and migration of T98G and U251 cells in vitro, and its knockdown affected glioma cell proliferation in vivo." (PMID 39492838, 2024). "Clustering and typing of IDH wild‐type gliomas was undertaken using the IRF7 regulon." (PMID 39492838, 2024). "Moreover, the prognostic analysis revealed that patients in the IRF7 high‐expression group had a worse prognosis in The Cancer Genome Atlas (TCGA) and Chinese Glioma Genome Atlas (CGGA) cohorts (p < 0.05)." (PMID 39492838, 2024). "Notably, an upregulation of IRF7 was observed in the IDH‐negative glioma tissues, which were frequently encircled by macrophages or microglia." (PMID 39492838, 2024). "In wild‐type IDH gliomas, the IRF7 regulon gene was highly expressed in the center of the tumor." (PMID 39492838, 2024).
glioma (continued). "In the GL261 glioma model, which was defined as an immunotherapy-sensitive glioma model, increased expression of M1 macrophage markers (Tnfa, Irf7, and Ifng) and decreased expression of M2 macrophage markers (Arg1, Cd206 and Cd163) were found after treatment with anti-PD1 immunotherapy." (PMID 37543576, 2023). "IRF7 was involved in the immune response of low-grade glioma to influence tumor progression." (PMID 36189255, 2022). "Among the nine members, IRF7, the master regulator of transcriptional activation of type I interferon genes, was found to be over-expressed in glioma cells and specimens, promoting microglia recruitment and tumor growth by increasing expression of inflammatory cytokines." (PMID 33902005, 2021). "Furthermore, IRF7 depletion could suppress glioma progression and decrease cellular heterogeneity in vivo through interleukin-6 and Notch signaling." (PMID 33902005, 2021). "The expression of IRF7 was reported to be positively correlated with the enrichment of tumor-infiltrating CD8+T cells and M1 macrophages in glioma; a similar result has been reported in colorectal cancer." (PMID 38698468, 2024). "Immunofluorescence staining revealed distinct patterns of IRF7 and IBA1 expression in IDH‐negative and IDH‐positive glioma tissues." (PMID 39492838, 2024). "IRF7 was not only differentially expressed but also involved in crucial signaling pathways and immune responses specific to IDH wild‐type gliomas." (PMID 39492838, 2024). "CSF2 depletion from both LN18 and U87 glioma cells blocked up-regulation of the anti-inflammatory IL10 expression and led to induction of IRF7 and IL1β mRNA levels in stimulated microglia." (PMID 32390004, 2020). "Meanwhile, IRF7, MX2, and OAS1 are key mediators in immune regulatory pathways, and their overexpression may facilitate immune evasion in gliomas." (PMID 40365337, 2025). "Overall survival curves indicated that glioma patients with lower IRF1 (p = 4.42E-33), IRF2 (p = 2.22E-16), IRF3 (p = 1.43E-15), IRF4 (p = 0.004), IRF5 p = 5.84E-12), IRF7 (p = 6.85E-28), IRF8 (p = 0.001), and IRF9 (p = 0.000) transcript levels had significantly longer overall survival times." (PMID 33902005, 2021). "Among the 260 grade II, 267 grade III, and 173 grade IV glioma patients, significant correlations were observed between IRF1 (p = 8.00E-61), IRF2 (p = 6.80E-18), IRF3 (p = 1.70E-23), IRF5 (p = 2.30E-08), IRF7 (p = 1.90E-29), IRF8 (p = 0.029), IRF9 (p = 4.80E-05) expression and pathological grade." (PMID 33902005, 2021). "Moreover, we observed upregulation of IRF7 mRNA and Il1b mRNA in human microglia upon stimulation with CSF2-depleted LN18 or U87 glioma cells, respectively, relative to treatment with shNeg-conditioned medium." (PMID 32390004, 2020). "In addition, microarray analysis revealed that the PDGFB-driven glioma had a significant increase in other anti-inflammatory (M2) mediators, including IL1R2, IRF7, and STAT3." (PMID 33020472, 2020). "We found that IRF1, IRF2, IRF5, IRF7, IRF8, and IRF9 were upregulated in glioma compared with normal tissue." (PMID 33902005, 2021).
ZIKV infection (14 papers, 2017 to 2025). "Because of the ZIKV infection interferon receptor (Ifnar1-/-) or Irf3-/-Irf5-/-Irf7-/-, triple-knockout mice developed neurological disease and sustained high viral loads in the brain, spinal cord, and testes." (PMID 36831177, 2023). "Previous work has demonstrated that wild-type immunocompetent mice are resistant to ZIKV pathogenesis but that mice lacking alpha/beta interferon (IFN-α/β) signaling (e.g., Ifnar1−/−, A129, AG129, Irf3−/− × Irf5−/− × Irf7−/−) succumb to ZIKV infection." (PMID 28270583, 2017). "Numerous studies have shown that ZIKV interacts with sensory molecules, such as toll-like receptor 3 (TLR3) and retinoic acid inducible gene 1 (RIG-1), as well as the transcription factors interferon regulatory factor 3 (IRF7) and NFκ-B, following ZIKV infection." (PMID 36014974, 2022). "In support of this hypothesis, we saw that Ifnar1−/− mice had a very similar delayed pattern of sensor and Irf7 induction in the FRT after ZIKV infection." (PMID 31554802, 2019). "The main transcription factors in innate immunity to ZIKV infection include NF-κB, IRF-3, and IRF-7." (PMID 36831177, 2023). "Molecules involved in type I IFN signaling are also increased by ZIKV infection, such as STAT1, DDX60L, DDX60, DDX58, STAT2, and IRF7." (PMID 36142200, 2022). "We evaluated the crosstalk between RIG-I and DNA-PKcs during ZIKV infection analyzing the IFN-I/III-inducing transcription factors including IRF1, IRF3, IRF5, IRF7, and p65 (NF-κB subunit)." (PMID 36311766, 2022). "Our study also found that in CHME3 cells ZIKV infection resulted in upregulation of type I interferon (IFNβ), interferon-stimulated genes (MX-1 and ISG15), pattern recognition receptors (RIG-I and MDA5) and IRF7." (PMID 32373079, 2020). "This study noted the induction of ATF3, EGR1, JUNB, IRF7, ISG15, HERC5/6, additional ISGs, chemokines CCL5 and CXCL10, prosurvival responses, and decreased proapoptotic genes, similar to gene induction levels we found to be induced by ZIKV infection of hBMECs (GEO GSE98889)." (PMID 28698279, 2017). "We observed that ZIKV infection induces IRF1 and IRF3, but not IRF5 and IRF7 nuclear accumulation." (PMID 36311766, 2022).
influenza pneumonia (12 papers, 2020 to 2025). "To assess the effect of impaired antiviral immunity on the development of severe viral bronchiolitis, we inoculated WT (+/+) and IRF7-deficient (-/-) neonatal (7 day old) mice with pneumonia virus of mice (PVM)." (PMID 32658914, 2020).